LEP (leptin)
Diseases named in the same sentence as LEP in open-access papers (continued):
Sharing a sentence is not in itself a finding about the gene and the disease.
Obesity (continued). "Leptin, adiponectin, and resistin represent a set of hormones associated with the development of CVD, obesity, T2DM, and insulin resistance, and are modified in obese/overweight people compared to normal-weight individuals." (PMID 33946540, 2021). "As obesity progresses, adipocytes release adipokines such as leptin, adiponectin, resistin, and visfatin from adipose tissue, which is considered to be a metabolic endocrine organ." (PMID 33668426, 2021). "By contrast, obesity has been positively correlated with high levels of both leptin and IgE, aggravating AD in rats." (PMID 34827640, 2021). "Leptin levels with notable sexual dimorphisms changes significantly in early obesity and was observed to also correlate with insulin levels." (PMID 34439950, 2021). "These authors found a significant reduction in leptin plasma levels after 1-year of a lifestyle intervention in adolescents with obesity." (PMID 33498461, 2021). "Taken together, cell-intrinsic leptin insensitivity, caused at least in part by ER stress, appears to be a major driver of central leptin resistance in obesity." (PMID 34613819, 2021). "Leptin also regulates bone metabolism; hypothalamic or subcutaneous administration of leptin has been shown to impair obesity-induced marrow adiposity." (PMID 34912805, 2021). "Increasing adipose tissue mass in obesity directly correlates with elevated circulating leptin levels." (PMID 34064112, 2021). "The primary lack of functional leptin signaling in CLD causes hyperphagia and severe obesity, so that CLD is distinguishable from physiologic states of low leptin associated with negative energy balance/starvation." (PMID 34002033, 2021). "Obesity is involved in the alteration of adipokines; adiponectin and leptin which are known to regulate blood pressure, lipid and glucose metabolism and inflammation and also associated with MetS." (PMID 34844584, 2021). "PNE decreased body weight, fat mass, plasma leptin levels, and improved glucose metabolism after high-fat-induced obesity." (PMID 33919440, 2021). "Elevated serum leptin levels directly correlate with increasing adipose tissue mass and is a major driving force for obesity and related metabolic perturbations." (PMID 34064112, 2021). "Obesity alters the levels of certain adipokines, and although there was an upper BMI limit of ≤30 kg/m2 in our study, we identified leptin and IL-8 as being positively correlated with BMI." (PMID 34063149, 2021). "It has been theorized that the observed association of IL1 cytokine family genes with obesity in mice may be due to leptin dysregulation and consequent hyperphagia rather than direct modulation of adipocyte function because Il1r1 and Il6 KO mice develop leptin resistance." (PMID 34834553, 2021). "Leptin levels are found to be higher in obese patients in comparison with lean patients contributing to the chronic inflammation that occurs in obesity." (PMID 34212054, 2021). "Vitamin D and adipokines, such as leptin and adiponectin, are possible mediators connecting obesity and SLE." (PMID 33557015, 2021). "Moreover, our study provided further evidence that adipokines, particularly leptin, could have an important role in disease pathogenesis and be associated with systemic comorbidities, such as obesity, which may be determined already at the level of the genetic background." (PMID 34685457, 2021). "Vice versa, obesity-associated plasma factors such as FAPB4, leptin, and LDL-cholesterol represent metabolically affected adolescents with chronic disease, who are often not obese at all." (PMID 34635725, 2021). "The effect of three types of energy-restricted diets on the leptin concentration of 21 women with obesity was assessed during 4 weeks: 1) total fast, 2) ≈455 kcal in total, mainly from protein, and 3) 50% maintenance energy." (PMID 34899599, 2021).
Obesity (continued). "In this study, down-regulation of gene expression of PPARγ, C/EBPα, SREBP-1c, aP2, FAS, LPL, and leptin in 3T3-L1 adipocytes by 18KHT01 suggested the potential effect of 18KHT01 on preventing adipogenesis, so prevent obesity." (PMID 34975503, 2021). "In fact, approaches to decrease leptin levels have been shown to be effective in countering obesity and obesity-related comorbidities." (PMID 33761942, 2021). "In this context, we will focus briefly on the DIO model, the most frequent experimental model used to study leptin resistance, since it shares many characteristics with human obesity, including an attenuated response to the anorexigenic effect of leptin." (PMID 34208585, 2021). "Obesity is an inflammatory disorder in which adipokines, as resistin or leptin, are secreted and play an important role in EMT." (PMID 34573003, 2021). "The results show that inhibition of Kdm6a reduces the Cry1 expression and sensitizes leptin signaling to combat obesity‐related disease." (PMID 34306972, 2021). "In mammals, leptin is a hormone secreted by adipocytes and acts on the hypothalamus to suppress eating and obesity." (PMID 34759838, 2021). "Obesity is also associated with leptin-resistance and MMP-dependent cleavage of leptin is a mechanism underlying leptin-resistance in obesity." (PMID 33854178, 2021). "Many studies have shown that LEP functions far beyond metabolism alone, and is the main mediator of obesity-related cancers, such as colorectal, prostate, and breast cancers." (PMID 34414945, 2021). "Further, endospanin-1 knockdown mice (targeting hypothalamus) are highly leptin sensitive and resistant to diet-induced obesity." (PMID 35069248, 2021). "Although leptin was thought to be an anti-obesity hormone owing to its metabolic effects, obese individuals develop leptin resistance disrupting its satiety and weight-reducing effects." (PMID 33761942, 2021). "The descriptors employed, being collated according to the MeSH and DeCs thesauri, were: leptin, obesity, inflammation, cancer, immunotherapy, treatment, immune system." (PMID 34202969, 2021). "In accordance with earlier findings, we previously demonstrated that leptin at concentrations relevant to obesity upregulates a potent proatherogenic protein, thrombospondin-1 (TSP-1) expression, in human and murine aortic SMC primary cultures." (PMID 34064112, 2021). "In contrast, the impact of a lower reduction of leptin levels on the immunomodulatory capacity of individuals with obesity, obtained adding bouts of exercise above the AT, is hard to explain at present." (PMID 34047810, 2021). "LEP, known as the obesity hormone, is also secreted by the ovary, placenta, bone marrow, and mammary gland." (PMID 34884678, 2021). "The discovery of leptin begins with a mouse model in the Jackson laboratory; where the ob gene was identified as a key regulator for obesity." (PMID 33849593, 2021). "Molecular analysis of the brain in the same model, in addition to HFD-fed mice, showed that obesity rapidly increases LepR expression in astrocytes where it then influences the leptin-induced calcium signaling in astrocytes." (PMID 34201099, 2021). "In contrast to ghrelin, levels of circulating leptin are increased in individuals with obesity, who typically develop a resistance to leptin signaling." (PMID 34404907, 2021). "Hallmarks of obesity include adipocytokine dysregulation where hyperleptinemia (high leptin levels) is closely tied with higher BMI." (PMID 34389732, 2021). "The concept of leptin resistance implies the processes that result from a state of obesity impair the effects of leptin, thereby contributing to the formation of obesity and obstructing the potential efficacy of therapy with the use of exogenous leptin." (PMID 34084149, 2021). "In the present section, we discuss the molecular mechanisms controlling primordial to primary follicle transition, and how obesity and altered leptin signaling can jeopardize its regulation." (PMID 33924072, 2021).
Obesity (continued). "Leptin and leptin resistance are closely related to the occurrence and development of simple obesity." (PMID 34646336, 2021). "This literature review aimed to reviewing recent developments and publications concerning the role of obesity, leptin, and miRNA deregulation in adverse prognosis of breast cancer." (PMID 33482868, 2021). "Experiments conducted in the early 1990s showed that defects in the transport of leptin through the BBB played a major role in the pathogenesis of obesity." (PMID 34438908, 2021). "Infection with H. pylori leads to lower levels of ghrelin and leptin compared to other healthy people in the community, which in turn increases obesity and metabolic syndrome." (PMID 34922625, 2021). "Circulating leptin levels are in strong positive correlation with BMI and the amount of adipose tissue; in developing obesity, leptin secretion increases and aims to resist weight gain." (PMID 34835949, 2021). "AT also produces pro-inflammatory adipokines, and their expression is enhanced by obesity, such as leptin, TNFα, and interleukin-6 (IL-6)." (PMID 34836382, 2021). "Colorectal cancer (CRC) is also attributed to overweight and obesity and available data suggest that CRC risk is positively correlated with many factors, including metabolic syndrome or leptin levels." (PMID 34202969, 2021). "This study utilized the Db/Db genotype as well as the Western diet to enhance obesity and diabetes due to impaired leptin signaling." (PMID 32374776, 2020). "Given that dysfunctional leptin signaling is highly correlated with metabolic diseases such as obesity and T2DM, we used ZDF rats as the T2DM model." (PMID 32920548, 2020). "Furthermore, Hager and colleagues assessed the role of genetic variation in determining protein level variation in obesity and suggested that rare polymorphisms in the Bag6 gene might be associated with the observed changes in leptin protein expression in subjects with type 2 diabetes." (PMID 31911483, 2020). "Leptin resistance has also been observed in cases of obesity, due to reduced sensitivity of LepR to leptin, resulting in an impaired modulation of satiety." (PMID 33218163, 2020). "Our laboratory has utilized mouse models of obesity, and shown that leptin is a powerful respiratory stimulant, which dramatically increases the hypercapnic response and HVR." (PMID 32698380, 2020). "It has been reported that deregulation of leptin production or availability during pregnancy could alter foetal growth through inappropriate placental development and function and program offspring to a higher risk of developing metabolic diseases, such as obesity." (PMID 32825787, 2020). "Collectively, these observations indicate that PAI-1 plays a role in aggravating leptin resistance during obesity development." (PMID 32670063, 2020). "In this study, we found that maternal resveratrol treatment can reduce maternal HF diet/obesity-induced retroperitoneal adiposity plus leptin dysregulation in the offspring." (PMID 32316577, 2020). "We have also previously shown recovery of hypothalamic leptin resistance and normalisation of hypothalamic satiety pathways after a period of postnatal obesity that led to disruption of the hypothalamic metabolic circuitry." (PMID 33396616, 2020). "Diet-induced obesity led to significantly increased leptin levels in the plasma of mice, compared to their corresponding control diet-fed groups." (PMID 33244094, 2020). "Adipose tissues produce several proinflammatory cytokines such as TNF-α, leptin, resistin, and adiponectin, which have been suggested as being responsible for linking obesity and metabolic syndrome." (PMID 32823524, 2020). "Another study also reported anti-obesity and anti-lipidemic effects related to hepatic AMPK activation in HepG2 and leptin-deficient mice." (PMID 33371201, 2020).
Obesity (continued). "In a preclinical melanoma model diet induced obesity led to a leptin-dependent decrease in functional DCs and tumor infiltrating CD8+ T cells indicating impairment of an anti-tumor response." (PMID 32549336, 2020). "In summary, the disease-causing variants in the LEPR gene found in the two patients interrupt the leptin-melanocortin signalling pathway and lead to severe early-onset obesity, pronounced hyperphagia, and permanent food-seeking behaviour." (PMID 33140236, 2020). "A link between obesity, inactivity and raised circulating leptin concentrations has been clearly demonstrated, which suggests that high circulating leptin concentrations are ineffective in regulating appetite and body mass when physically inactive." (PMID 32729763, 2020). "Metabolic peptides—leptin and ghrelin—appear to be altered in depression, revealing a potential link between obesity and mood disturbances." (PMID 33255237, 2020). "Further, we assessed other measures that are associated with metabolic health status in obesity: HOMA-IR, leptin, body fat percentage, WHtR, WHR, and FMI." (PMID 33328935, 2020). "Mice with neuronal deletion or POMC-neuron-specific deletion of PTP1B display increased leptin sensitivity and energy expenditure, and reduced DIO susceptibility, suggesting that increased PTP1B expression in obesity suppresses leptin signaling." (PMID 32731387, 2020). "More importantly, GCs are required for the development of both genetic and diet-induced obesity and interact with leptin signaling." (PMID 33335471, 2020). "We suggest that this neuropathway becomes important in obesity, in which elevated leptin maintains the hypothalamic pituitary thyroid axis, despite leptin resistance." (PMID 32538782, 2020). "Both biomarkers were lower in children with overweight and obesity in our study, while leptin levels were elevated." (PMID 33266497, 2020). "In this study, we found that resveratrol treatment in dams with HF diet/obesity can improve leptin dysregulation of the offspring by decreasing leptin/sOB-R ratio." (PMID 32316577, 2020). "Much work has shown that leptin can promote the activation of T cells while also promoting MDSC formation in obesity." (PMID 32244756, 2020). "In humans, congenital leptin deficiencies are rare, leading to hyperphagia and early-onset obesity, which can be reversed with a leptin replacement therapy." (PMID 33210603, 2020). "In patients with obesity, while the leptin levels are increased, leptin receptor (LEPR) signaling is attenuated." (PMID 33105727, 2020). "The expression of adiponectin decreases with an increase in adiposity, while leptin levels increase in obesity." (PMID 32821266, 2020). "One molecular mechanism implied in this finding is that the defection of primary cilia diminishes hypothalamus neurons LepR trafficking to or near the cilium, effectively halting the effects of leptin on satiety and so contributing to obesity." (PMID 33139642, 2020). "Adipose tissue-secreted hormones such as leptin and resistin have significant roles in the initiation and progression of many metabolic disorders such as obesity and diabetes." (PMID 33007981, 2020). "Together, leptin and adiponectin generally show opposite molecular effects on obesity and cellular behaviors." (PMID 32486076, 2020). "Pathogenic variants in genes involved in the hypothalamic leptin–melanocortin pathway, including melanocortin-4-receptor (MC4R), have been associated with monogenic obesity." (PMID 32153512, 2020). "Different studies in diet-induced obesity mice and obese humans suggest central resistance to different metabolic hormones that control food intake, such as leptin or GLP-1." (PMID 33126672, 2020). "In the in vivo studies mentioned in this review, the different effects of propolis on obesity have been reported through various mechanisms suppressing feeding in mice, inducing leptin in adipocytes, reducing adipose tissue mass, and improving dyslipidemia." (PMID 33383693, 2020).
Obesity (continued). "Treg cell proportions are also specifically decreased in the adipose tissue in diet-induced obesity, where leptin levels are expected to be highest." (PMID 33584724, 2020). "These parameters are determined with the leptin/adiponectin ratio, which is elevated in obesity and a marker of the adipose tissue production of pro-inflammatory cytokines and of insulin resistance in nondiabetic individuals." (PMID 32012794, 2020). "During obesity, dysregulations of adipose tissue induce an increase in pro-inflammatory adipokine secretions, such as leptin and oestrogen secretions." (PMID 32472095, 2020). "An important advantage of the Px model is that it reflects the isolated effects of reduced beta cell mass, without the potential multiple-organ toxic effects of STZ24 or the confounding effects of obesity and impaired leptin signaling found in e.g. ZDF rats." (PMID 32999377, 2020). "The obesity-related adipokine leptin has been well characterized as a growth factor for breast cancer and has been recently proposed to decrease sensitivity to tamoxifen in vitro." (PMID 32260113, 2020). "Since obese women and women with GDM show high circulating leptin levels and are hence considered leptin-resistant, we have identified nutritional strategies to counteract leptin resistance in both obesity and GDM." (PMID 32630697, 2020). "One group has investigated the role of leptin in mast cell function and the subsequent effect on macrophages in the context of obesity." (PMID 33584724, 2020). "Both excessive compressive mechanical force and high fat diet induced obesity caused TMJ osteoarthritis-like changes and increased expression of IL-1β, MMP-3, and leptin." (PMID 33060739, 2020). "For instance, study populations with obesity class 1 (BMI 30–34.9 kg/m2) and class 3 (BMI ≥ 40 kg/m2) are afflicted differently by hyperinsulinemia, hyperleptinemia, insulin and leptin resistance or low ghrelin levels." (PMID 32721994, 2020). "Resistance training represents a relevant non-pharmacological treatment in improving body composition and obesity biomarkers, expressed by reduced visceral and epididymal fat pad and plasma leptin levels." (PMID 32714085, 2020). "Increased circulating levels of leptin (a proinflammatory adipokines) in obesity lead to hypothalamic leptin resistance, turning down anorexigenic and energy expenditure signals and further contribute to aggravate obesity." (PMID 31935815, 2020). "In line with this, it has been demonstrated that blockade of endogenous leptin increases body fat mass to the same extent in mice with diet-induced obesity as in lean mice." (PMID 32510046, 2020). "High leptin levels can induce cancer cell proliferation and thus provide a link between obesity and cancer progression." (PMID 32604970, 2020). "The present study reports that MyD88 signaling in astrocytes is a key mediator of obesity pathogenesis and highlights its contribution to over-nutrition-induced reactive gliosis and leptin resistance in the hypothalamus." (PMID 32560726, 2020). "In these mice, we found extremely high levels of leptin, which can be explained by obesity and defective leptin signaling." (PMID 32340263, 2020). "For example, various adipocytokines (e.g., adiponectin, apelin, chemerin, leptin) are secreted from adipocytes, but in obesity, the regulation of the production of these adipocytokines is aberrant due to enlarged adipocytes." (PMID 33110098, 2020). "Diet-induced obesity in rodents, who were given high doses of leptin (an appetite suppressor), reduced food intake, but this effect lasted only around two weeks." (PMID 33153014, 2020). "Emerging evidence has shown an important role of the microbiota–gut–brain axis in the control of food intake by the hypothalamus and in insulin and leptin signaling in the contribution to evolution of obesity." (PMID 32825073, 2020). "Several studies on the association of LEP (OMIM: 164160; GenBank: NC_000007.14) polymorphisms with BMI or obesity have been conducted." (PMID 31914480, 2020).